BRINP3-DT (BRINP3 divergent transcript)
Synonyms: LINC01351
Gene: Long non-coding RNA gene on chromosome 1 (190,474,871 to 190,481,555, forward strand). Ensembl gene ENSG00000237457.
Diseases named in the same sentence as BRINP3-DT in open-access papers:
BRINP3-DT is named in the same sentence as 2 diseases in open-access papers, as found by Europe PMC text mining. Sharing a sentence is not in itself a finding about the gene and the disease.
BRINP3-DT shares sentences with these, for which no sentence is quoted: adenoma (1 paper); colorectal cancer (1).